ZNF773 (zinc finger protein 773)
Description:
May be involved in transcriptional regulation.
Synonyms: ZNF419B; MGC4728
Tractability: PROTAC: ubiquitination databases record sites on it.
Gene: Protein-coding gene on chromosome 19 (57,499,915 to 57,518,404, forward strand). Ensembl gene ENSG00000152439.
Subcellular location: Nucleus
Subcellular location (Human Protein Atlas): Nucleoplasm; Nucleoli fibrillar center
Pathways (Reactome):
Gene expression (Transcription): Generic Transcription Pathway
Gene Ontology:
Molecular function: protein binding; DNA-binding transcription factor activity, RNA polymerase II-specific; RNA polymerase II cis-regulatory region sequence-specific DNA binding
Biological process: regulation of transcription by RNA polymerase II; regulation of DNA-templated transcription
Cellular component: nucleus
Genetic constraint (gnomAD): Loss-of-function variants: 11 observed, 13.3 expected, observed/expected ratio (o/e) 0.83, 90% interval 0.52 to 1.37. The upper end of that interval is the gene's LOEUF score, 1.37, which puts it in group 5 of 6, group 1 being the genes least tolerant of losing a copy. Missense variants: 518 observed, 533.07 expected, observed/expected ratio (o/e) 0.97, 90% interval 0.9 to 1.04. Synonymous variants: 175 observed, 180.87 expected, observed/expected ratio (o/e) 0.97, 90% interval 0.86 to 1.1.
Homologues: Orthologues: macaque ZNF773 (95% identical), pig ZNF773 (74% identical), rabbit ZNF773 (71% identical), rat Zfy1 (24% identical), mouse Zfy1 (24% identical), tropical clawed frog zfx (23% identical), mouse Zfy2 (23% identical), zebrafish zfx (22% identical). Paralogues in human: ZNF419 (91% identical), ZNF256 (54% identical), ZNF304 (54% identical), ZNF792 (51% identical), ZNF551 (50% identical), ZNF549 (48% identical), ZNF587B (48% identical), ZNF418 (47% identical), ZNF548 (47% identical), ZNF772 (45% identical), ZNF570 (44% identical), ZNF583 (44% identical), and 26 more.
Diseases named in the same sentence as ZNF773 in open-access papers:
ZNF773 is named in the same sentence as 4 diseases in open-access papers, as found by Europe PMC text mining. Sharing a sentence is not in itself a finding about the gene and the disease. The quoted sentences say what the papers report.
colorectal cancer (1 paper, 2021). A primary or metastatic malignant neoplasm that affects the colon or rectum. "The trans-targets RPS21 and ZNF773 are also associated with colorectal cancer." (PMID 33957961, 2021).
liver cancer (1 paper, 2025). An epithelial or non-epithelial malignant neoplasm that arises from the liver. "It has been suggested that coffee-derived exosomes may protect against liver fibrosis and liver cancer by targeting Zinc Finger Protein 773 (ZNF773) and lysine N-methyltransferase 2C (KMT2C) genes through the miRNAs they carry." (PMID 40149930, 2025).
schizophrenia (1 paper, 2021). A major psychotic disorder characterized by abnormalities in the perception or expression of reality. "The genes ZNF773, PCNT, and DYSF were assigned the highest weights by the neural network and were thus considered to be the most predictive genes for schizophrenia." (PMID 34535759, 2021). "We applied the framework to seventeen phenotypes and found well-replicated genes such as HERC2 and OCA2 for hair and eye color, and novel genes such as ZNF773 and PCNT for schizophrenia." (PMID 34535759, 2021).
ZNF773 also shares sentences with these, for which no sentence is quoted: liver fibrosis (1 paper).